KRAS (KRas proto-oncogene, GTPase)
Diseases named in the same sentence as KRAS in open-access papers (continued):
Sharing a sentence is not in itself a finding about the gene and the disease.
squamous cell carcinoma (continued). "Some researches revealed the presence of squamous cell carcinoma (SCC), wild-type EGFR or KRAS gene mutations was associated with high expression of PD–L1, providing potentially benefits for the administration of PD-1/PD–L1 blockade in lung cancer." (PMID 32587276, 2020). "Combination of IPA-3 or OTSSP167 and auranofin was highly synergistic in EGFR or KRAS mutant adenocarcinoma and squamous cell carcinoma cell lines and decreased tumor volume in mice models." (PMID 31660987, 2019). "KRAS is mutated in 15-25% of NSCLC, mostly adenocarcinoma and occasionally squamous cell carcinoma, and is more frequent in white than in Asian populations (25–50% vs 5–15%, respectively)." (PMID 29464099, 2018). "In our patient cohort, we found significantly more frequent somatic KRAS mutations in cervical adenocarcinoma, whereas PIK3CA mutations were more frequently found in squamous cell carcinoma (manuscript submitted)." (PMID 25795131, 2015). "Tumor genotyping showed a KRAS mutation in codon 12 in three adenocarcinoma tumors, and a missense STK11 gene mutation in the squamous cell carcinoma." (PMID 25360587, 2014). "Lentivirus-delivered small hairpin RNAs were employed to specifically reduce AREG or EREG gene expression in wild-type KRAS A431 squamous cell carcinoma cells." (PMID 22491422, 2012). "These included 12 adenocarcinomas, 9 squamous cell carcinomas and 1 large cell carcinoma, all examined for known EGFR/KRAS/NRAS/HRAS/PI3K mutations." (PMID 19806209, 2009). "EGFR and KRAS G12C mutations were found almost exclusively in adenocarcinoma (7.8% and 13.3%, respectively), with very low prevalence in squamous carcinomas or NOS/other categories/not classified (p < 0.001 for both)." (PMID 40867330, 2025). "First, secondary KRAS mutation or KRAS amplification; second, alternative oncogenic alterations activating the RAS signaling pathway but not directly KRAS itself; and third, histological transformation from adenocarcinoma to squamous cell carcinoma." (PMID 35267628, 2022). "There were 3 non-adenocarcinoma patients harboring KRAS mutation (2 with squamous cell carcinoma and 1 with carcinoma not otherwise specified)." (PMID 35980949, 2022). "Emerging evidence suggests that KRAS could play an important role in squamous cell carcinoma; however, its role in oral squamous cell carcinoma (OSCC) is largely unknown." (PMID 36532636, 2022). "In total, 42% of those patients showed a putative resistance mechanism to adagrasib, including secondary mutations or amplifications to KRAS; the activation of the RTK–RAS signaling pathway; and the histological transformation of adenocarcinoma to squamous cell carcinoma." (PMID 36012655, 2022). "Also, within the NSCLC category, squamous cell carcinomas and non-G12C KRAS mutant adenocarcinomas, and other less common categories of NSCLC have no specific targetable therapies to date." (PMID 36136862, 2022).
squamous cell carcinoma (continued). "The present study aimed to examine the KRAS expression in oral epithelial dysplasia and squamous cell carcinoma of the oral cavity and to correlate its expression with the established prognostic markers (Ki-67, bcl2, and Cyclin D1) and the available clinicopathologic factors." (PMID 36532636, 2022). "However, in squamous cell carcinoma (SCC) of the lung, KRAS mutations are rare and their impact on clinical outcome is poorly understood." (PMID 34976827, 2021). "For instance, all the driver mutations of KRAS occurred in adenocarcinoma patients (21/61), while not detected in squamous cell carcinoma patients." (PMID 33078899, 2020). "The effect of IPA-3 (PAK1 inhibitor) plus auranofin (PKCι inhibitor) combination was evaluated by cell viability assay, colony formation and western blotting assay, using three types of NSCLC cell lines: EGFR or KRAS mutant adenocarcinoma and squamous cell carcinoma with PAK1 amplification." (PMID 31660987, 2019). "On similar lines, KRAS gene mutation has been reported in approximately 30–40% of adenocarcinomas but rarely in squamous cell carcinoma, small cell lung cancer or tumors from non-smokers." (PMID 28985714, 2017). "For squamous carcinoma corresponding proportions were 4.4% (11.1% with KRAS) vs 2.2%." (PMID 28415793, 2017). "This PIK3CA-EGFR/KRAS co-mutation was more common in never smokers than in current or former smokers (p = 0.039), and in adenocarcinoma than in squamous cell carcinoma (p<0.0001)." (PMID 24533074, 2014). "On the other hand, the identification of KRAS mutations in 17% of adenocarcinoma and in none of squamous carcinoma samples strongly suggests that they have distinct molecular profiles." (PMID 25220666, 2014). "Most notably squamous cell carcinomas are mostly commonly associated with smoking history and are marked by amplification of PIK3CA and p63; whereas adenocarcinomas are associated with a high frequency of mutations in KRas and EGFR." (PMID 24123619, 2013). "Moreover, the increased expression of KRAS protein was found in 17 (36.2 %) adenocarcinoma samples and in 37 (50.7 %) squamous cell carcinoma samples." (PMID 22537942, 2012). "None of the squamous cell carcinomas (0%: 0 out of 32) had detectable oncogenic mutations in either KRAS or BRAF." (PMID 21730982, 2011). "Notably, for patients with mKRAS mutations and squamous cell carcinoma, targeted treatment regimens and the addition of cetuximab, respectively, showed significant enhancements in survival rates, regardless of the KRAS mutation status." (PMID 39001401, 2024). "Interestingly, after further standardization of smoking status, we found that in non-smokers, male patients were more likely to have squamous cell carcinoma and KRAS mutations and less likely to have EGFR L858R mutation than female patients." (PMID 35061839, 2022). "The negative prognostic effect of KRAS mutations could also not be confirmed in other studies analysing bigger groups of patients with equally balanced adenocarcinoma vs squamous cell carcinomas." (PMID 19050706, 2009).
squamous cell carcinoma (continued). "Squamous cell carcinomas (including HNSCC, ESCC, and LSCC) are unique cancers, primarily driven by copy number gains and losses, rather than drivers with gain-of-function mutations such as KRAS and EGFR." (PMID 39605563, 2024). "In addition, within the NSCLC category, squamous cell carcinomas and non-G12C KRAS mutant NSCLC have no specific targetable therapies to date." (PMID 36136862, 2022). "Two models have been described where overexpression of KRAS, a member of the Ras family, coding for the K-Ras protein that is part of the RAS/MAPK pathway in the oral epithelium resulted in the growth of premalignant oral papillomas or dysplasia and squamous cell carcinoma." (PMID 35163485, 2022).
colorectal adenocarcinoma (120 papers, 1999 to 2026). The most common type of colorectal carcinoma. "Given that G12D and G12V are the most prevalent KRAS mutations in colorectal adenocarcinoma, we further analysed the differentially regulated genes in both mutant cell lines." (PMID 41266617, 2026). "Mutations in the KRAS proto-oncogene, particularly at codon 12, are among the most frequent genetic alterations in various cancers, and KRASG12V accounts for about 25% of all KRAS mutations observed in lung, pancreatic, and colorectal adenocarcinomas." (PMID 40794198, 2025). "The patient’s genetic profile, including a CHEK2 mutation, HER-2 positivity, and a KRAS mutation, significantly impacts the behavior of colorectal adenocarcinoma and its response to treatment." (PMID 39221315, 2024). "Researchers have even explored the predictive value of 2-[18F]FDG uptake in colorectal adenocarcinoma liver metastases (CLM) with regard to the KRAS mutational status." (PMID 38957833, 2024). "We also found that a high proportion of patients exhibited mutations in KRAS and that missense mutations occurred at a different codon than in colorectal adenocarcinoma." (PMID 38229035, 2024). "KRAS is frequently mutated in pancreatic cancer (88%), lung cancer (30%), and colorectal adenocarcinomas (50%)." (PMID 37370689, 2023). "It was reported that KRAS gene was often mutated in colorectal adenocarcinoma, and 88.9% (8/9) of KRAS mutated cases were stage III or IV diseases." (PMID 33836681, 2021). "We explore the predictive value of 2-[18F]FDG uptake with regard to the KRAS mutational status of colorectal adenocarcinoma liver metastases (CLM)." (PMID 33226505, 2020). "Mutual exclusivity of ARID1A and KRAS (all and specifically at residues G12 and G13) mutations in the colorectal adenocarcinoma patient cohort from the TCGA PanCancer Atlas (b)." (PMID 31217031, 2019). "Olevian and coworkers comparatively analyzed poorly-differentiated CNECs and poorly-differentiated conventional colorectal adenocarcinomas for mutations in KRAS and BRAF and for DMA mismatch repair protein abnormalities." (PMID 29652830, 2018). "The PBF-fixed samples of the 25 colorectal adenocarcinomas collected in the study had been routinely subjected to Sequenom MassARRAY® to screen for KRAS/NRAS/BRAF/PIK3CA mutations." (PMID 28796828, 2017). "First, we focused on cancer types known to have frequent activating mutations in KRAS or EGFR: colorectal adenocarcinoma (COAD) and glioblastoma multiforme (GBM), respectively." (PMID 26047463, 2015). "Although in colorectal adenocarcinoma the KRAS mutations are the most useful biomarker for selecting patients who are candidates for treatment with anti-EGFR monoclonal antibodies, its role in NSCLC as prognostic or predictive marker is less defined." (PMID 24782938, 2014). "In one study of colorectal adenocarcinoma, the frequency of different mutations (KRAS, BRAF, NRAS, and PIK3CA) were found to vary significantly with the location of the metastasis (lung, brain, and liver)." (PMID 23119210, 2012). "To illustrate the ability to find and visualize known mutations in the KRAS oncogene, we ran 3DVizSNP against a colorectal adenocarcinoma (COAD) vcf file from a single patient from the TCGA database with the flag ‘-g KRAS’ to select only variants in the KRAS gene." (PMID 37296383, 2023).
colorectal adenocarcinoma (continued). "Consensus clustering of all PDAC, cholangiocarcinoma, and colorectal adenocarcinoma samples based on the expression of the KRAS mutation status signature genes (genes conservatively DE in KRAS wildtype vs. mutant mPDAC; n = 227) revealed an optimal solution based on four clusters." (PMID 36209277, 2022). "Previous observations suggested that KRAS mutation status was highly homogeneous between areas of the primary tumor and the corresponding metastasis of colorectal adenocarcinomas, and KRAS mutation was associated with more rapid and aggressive metastatic behavior of colorectal liver metastases." (PMID 34993129, 2021). "KRAS mutation status is critical for targeted therapy in colorectal adenocarcinoma (CRAC)." (PMID 33585224, 2020). "KRAS (Kirsten rat sarcoma 2 viral oncogene homolog) is a major predictive marker for anti-epidermal growth factor receptor treatment, and determination of KRAS mutational status is crucial for successful management of colorectal adenocarcinoma." (PMID 32708359, 2020). "Indeed, examination of the TCGA PanCancer Atlas colorectal adenocarcinoma cohort revealed that KRAS mutations were mutually exclusive with ARID1A mutations with only 16 out 526 patients harboring mutations in both genes." (PMID 31217031, 2019). "Besides NSCLC, KRAS mutations are also frequent in other tumor types, such as pancreatic and colorectal adenocarcinoma (88% and 50% of all cases, respectively), with KRAS G12D mutations being the most common alteration among these histotypes (32% and 46% of all cases, respectively)." (PMID 36358848, 2022). "Our results suggest the potential utility of targeting ACSS2 in KRAS G12V colorectal adenocarcinoma." (PMID 40131933, 2025). "Two of eight carrying APC mutations also have KRAS p.G12V/D, which is a general oncogenic feature that was also observed in the five MSS colorectal adenocarcinoma samples also sequenced in our study." (PMID 40757636, 2025). "In contrast, KRAS mutations are rare in SCLC (approximately 1.6%); however frequently found in colorectal adenocarcinomas (~40%)." (PMID 41153242, 2025). "We observed that 10~30% of colorectal adenocarcinomas are associated with PIK3CA mutations, while 20~50% of patients are associated with a KRAS mutation status." (PMID 36652260, 2023). "A recent study reported that EGFR blockade reverts resistance to KRAS G12C inhibition in colorectal adenocarcinoma." (PMID 34647903, 2021). "Another study confirms the tumor suppressor roles of MIR193A by perturbing KRAS function in colorectal adenocarcinoma, including reducing cell proliferation, increasing apoptosis, and inhibiting epithelial-mesenchymal transition." (PMID 31523496, 2019). "To assess acquisition of anoikis resistance, we selected mutated KRAS (G12V) and BRAF (V600E) oncogenes owing to their clinical and biological relevance in colorectal adenocarcinoma." (PMID 31545494, 2019). "Compared with colorectal adenocarcinomas, neuroendocrine carcinomas exhibited a higher frequency of BRAF (37%) mutations, but a lower frequency of KRAS (21%) and APC (16%) mutations." (PMID 29652830, 2018). "The other six cell lines are colorectal adenocarcinoma cell lines: DLD-1 and HCT116 bear KRAS and PI3KCA mutations, SW620 bears KRAS mutation, HT29 and RKO bear BRAF and PI3KCA mutations and Colo205 cell line bears BRAF mutation." (PMID 27520705, 2016). "We first used CRISPR-based genome editing to generate a KRAS p.G13A mutant colorectal adenocarcinoma (SW48) stable cell line." (PMID 26788852, 2016). "Another worldwide common cancer is colorectal cancer, where 40% of colorectal adenocarcinoma are KRAS (v-Ki-ras2 Kirsten rat sarcoma viral oncogene homolog)-mutated." (PMID 27416070, 2016). "A Caco-2 (human colorectal adenocarcinoma) cell line stably expressing monomeric green fluorescent protein (GFP)-tagged oncogenic mutant KRAS (KRASG12V) was generated and transfected with siRNA pools comprising four different oligonucleotides against each gene." (PMID 38328115, 2025).